IL1B (interleukin 1 beta)
Diseases named in the same sentence as IL1B in open-access papers (continued):
Sharing a sentence is not in itself a finding about the gene and the disease.
depression (continued). "We also investigated the effect of CVS on the concentration of major cytokines associated with depression, i.e., IL-1β, IL6, and TNF-α in the blood of rats." (PMID 30533439, 2018). "Proinflammatory cytokine IL-1β in some brain areas of the limbic system, such as the prefrontal cortex and hippocampus of depressive rats, was implicated in the pathophysiology of depression." (PMID 29946236, 2018). "Clinical and preclinical settings often associate chronic stress exposure with major depressive disorders and enhanced pro-inflammatory cytokine levels, most consistently IL-1β and IL-6." (PMID 30142161, 2018). "Depression is associated with increased concentration of proinflammatory cytokines in circulation, such as IL-1β, IL-6, TNF-α, IFN-γ, and chemokines." (PMID 29351245, 2018). "Chronic mild stress has been shown to cause depression‐like behavior and induce the production of inflammatory cytokines such as IL‐1β and IL‐6 in rats." (PMID 29953737, 2018). "A paper on 773 elderly Koreans also found a significant association between IL-1β 3953 C/T and depression, however, this association was lost once a Bonferroni correction was applied." (PMID 27555379, 2017). "Although blockade of IL-1β is a viable therapeutic target for the treatment of depression, this approach faces several problems, such as the risk of serious infections due to systemic inhibition of IL-1β9." (PMID 28794421, 2017). "The over-expression of a number of genes, including Ifng and Il1b, in microglia relative to macrophages offered further evidence of transcriptome conditions associated with depression-like symptoms." (PMID 26959683, 2016). "In particular, evidence suggests that depression is associated with increased circulating concentrations of proinflammatory cytokines such as IL-1β, IL-6, TNF-α, and IFN-γ in association with elevations in chemokines and the acute phase protein, CRP." (PMID 26775294, 2016). "IL-1β is a pleiotropic cytokine linked to many sickness behaviors and responses including fever, pain and depression." (PMID 26469939, 2015). "Taken together, the present results suggest that possession of high expression alleles at IL6 and IL1β increase depression risk following interpersonal stress exposure in the present sample." (PMID 25596176, 2015). "Depression is also associated with aberrant activation of inflammation, such as increases in circulating levels of interleukin (IL)-1β, IL-6, and tumor necrosis factor-α (TNFα)." (PMID 25947540, 2015). "Plasma concentrations of proinflammatory cytokines IL-1 and IL-6 increase in patients with depression; in patients taking antidepressant medications, reduction of plasma IL-1β appears to be associated with the treatment." (PMID 25237578, 2014). "LPS-induced depression was associated with increments in IL-1β content in plasma and prefrontal cortex, TNF-α in plasma, and decreased nitrergic neurotransmission evident in the striatum and prefrontal cortex." (PMID 24999483, 2014). "Ja and Duman have demonstrated an essential role of the proinflammatory cytokine interleukin-1 beta (IL-1β) in the antineurogenic effects of chronic stress, a condition which represents a major risk factor for depressive disorders." (PMID 24678511, 2014). "In accordance with these data, it has been described that external stress-induced depression-like behaviors are associated with increased levels of certain cytokines, such as IL1β." (PMID 22520439, 2012). "A polymorphism (rs16944) in the interleukin-1beta (IL-1β) gene has also been reported to be associated with the medication response in depression." (PMID 21726461, 2011). "A few studies have examined genetic polymorphisms of the IL-1β gene for association with depression." (PMID 21726461, 2011). "Furthermore, alignment with IL1-β and IL-6R polymorphisms and its therapeutic outcomes in severe depression have been expressed." (PMID 39841732, 2025).
depression (continued). "IL-10, another key anti-inflammatory cytokine, suppresses the production of pro-inflammatory mediators such as TNF-α and IL-1β, while enhancing tissue regeneration and immune homeostasis.In depression-related studies, elevated IL-4 levels have been associated with better emotional stability." (PMID 40453075, 2025). "We previously identified a significant association between IL-1β and AD conversion in patients with depression, suggesting the neuroinflammatory hypothesis linking depression with AD." (PMID 39859090, 2025). "Depression is a multifaceted disorder caused by neuroinflammation, which is mainly demarcated by a significant increase in proinflammatory cytokines, including interleukin-1β (IL-1β), interleukin-6 (IL-6), and tumor necrosis factor-α (TNF-α)." (PMID 40487411, 2025). "Although existing studies have primarily focused on the effectiveness of established interventions on IL-1β, IL-1α—being the inducible form released in an inflammatory disease state—may be more closely associated with depression than IL-1β." (PMID 41194929, 2025). "Immune dysregulation, such as defective antigen presentation caused by interleukin 6 (IL-6) or an IL-1β-mediated hemophagocytosis-like syndrome, may play a role in depression." (PMID 41011169, 2025). "Association between major depressive disorders with IL1β rs1143627 polymorphism." (PMID 39841732, 2025). "Based on earlier study, IL-1β rs16944 and rs1143627 polymorphisms may increase the risk of depression." (PMID 39841732, 2025). "The antidepressant effects correlated with restored MBP, CNP, and IL-1β expression levels, suggesting that MBP/CNP deficiencies in depression may involve IL-1β elevation." (PMID 40500721, 2025). "Studies suggest that individuals with the C allele may experience more severe depressive symptoms and higher IL-1β expression, indicating a potential genetic risk factor for major depression." (PMID 39841732, 2025). "Association between major depressive disorders with IL1β rs16944 polymorphism." (PMID 39841732, 2025). "The multiple endocrine neoplasia type 1 (Menin) gene in astrocytes regulates neuroinflammation by inhibiting the NF-κB/IL-1β pathway; functional deficiencies or genetic mutations in Menin may contribute to the onset of depressive disorders." (PMID 40936908, 2025). "These polymorphisms in the IL1B gene have been found associated with several inflammatory diseases, infectious diseases, autoimmune disorders, depression, and several types of cancers such as hepatocellular carcinoma, lung cancer, breast cancer, gastric cancer, and lymphoblastic leukemia." (PMID 38858637, 2024). "Similarly, in human Men1, the discovery of SNP rs375804228 is linked to an increased risk of depression and results in abnormal activation of NF-κB and IL-1β production." (PMID 38916735, 2024). "Furthermore, acupuncture reduces inflammatory markers like LPS, TNF-α, and IL-1β in serum and brain, which are linked to anxiety and depression, suggesting dual benefits for gut and mental health." (PMID 38452033, 2024). "Another study used HPCs and recorded exposure to IL-1b to testthe potential rescue of dysregulation in the kynurenine pathway that leads todecreased neurogenesis linked to depression, using the antidepressants, sertraline,and venlafaxine, and the fatty acids, DHA, and EPA." (PMID 38954533, 2024). "However, due to the close association of TNFα and IL-1β with the pathophysiological processes of anxiety and depression, these two markers were explicitly investigated." (PMID 38731995, 2024). "In a cohort of 181 Taiwanese patients with chronic viral hepatitis, we investigated the impact of five common IL‐1β single nucleotide polymorphisms (SNPs), including rs16944, rs1143627, rs1143630, rs1143643, and rs3136558, on depressive symptoms using the Beck's Depression Inventory‐II." (PMID 37937732, 2024).
depression (continued). "However, polymorphisms in IL1B play a role in depression, multiple inflammatory-associated disorders including thyroid disease, arthritis, and septic shock, and susceptibility and response to infection." (PMID 38858637, 2024). "The rs16944 IL1B was associated with childhood abuse as a predictor of depression scores." (PMID 37510364, 2023). "A dysregulated HPA axis activity is proposed to be accompanied by the overproduction of pro-inflammatory cytokines such as tumor necrosis factor alpha (TNF-α), interleukin (IL)-6, or IL-1β, which leads to the loss of hippocampal neurogenesis and promotion of depression-like behaviors." (PMID 37238920, 2023). "Genetic polymorphisms in the IL1B gene have been well studied in depression." (PMID 37510364, 2023). "We hypothesize that specific depression symptoms are related to distinct inflammatory variables, and IL-1β may be linked to more severe anxiety/somatization, sleep disruption, and body weight issues." (PMID 37692303, 2023). "Furthermore, resistance exercise exerts an anti-inflammatory effect by down-regulating pro-inflammatory markers such as TNF-α and IL-1β mRNA, which have been implicated in depression." (PMID 37333923, 2023). "Moreover, several depression-linked genetic variants in pro-inflammatory genes, including in IL1B, TNFA, and CRP, are associated with decreased expression." (PMID 37217515, 2023). "Many important chronic diseases, including depression, various malignancies, autoimmunity, and AD, have been linked to pathological activation of the inflammasome and increased production of IL-1β." (PMID 37190098, 2023). "The levels of tumor necrosis factor-alpha (TNF-a) interleukin-1 beta (IL-1b), and interleukin 6 (IL-6) were found to be associated with depression severity as measured by BDI II, while levels of Interleukin-2 (IL-2) were found to be correlated with anxiety measured by STAI-state." (PMID 37250694, 2023). "IL-1β has been implicated in the pathophysiology of major depression." (PMID 37510364, 2023). "The CDAI was developed based on its combined effect on anti-inflammatory effects based on the pro-inflammatory markers Tumor Necrosis Factor-α (TNF-α) and Interleukin-1β (IL-1β), which are associated with many health outcomes, including depression, all-cause mortality, colorectal cancer, etc.." (PMID 37063339, 2023). "In agreement with the key role of caspase-1 in the MDD, in our study, CRS significantly increased the expression of caspase-1-IL-1β in the serum and hippocampus, and genetic deficiency of caspase-1 prevented CRS-induced depression-like behaviors via inhibiting the expression of IL-1β." (PMID 37369673, 2023). "Another study found that focused interventions for individuals with acute coronary syndrome with high IL-1β levels may reduce the risk of future depression." (PMID 36685498, 2022). "For example, having a homozygous rare allele of the −511 ​C ​> ​T SNP of interleukin-1 beta (IL-1β) was associated with higher depression risk, while having that of the rs1800795 and rs2069840 of interleukin 6 (IL-6) could confer higher depression severity." (PMID 35528795, 2022). "Furthermore, TNF-α, IL-1β, and IL-17 were positively associated with HADS-D score, while high IL-1β, IL-6, and IL-17 correlated with depression occurrence." (PMID 35239774, 2022). "Data about a strong association between IL-1β and frailty are limited and mainly related to the increased risk of cognitive decline and development of Alzheimer’s disease in the aged individuals or with depression in aged individuals." (PMID 36289502, 2022). "A significant cytokine associated with depression in the elderly is related to IL-1β." (PMID 36160713, 2022). "However, a gene‐based study of three SNPs in IL1B reported that the C allele of rs1143643 was associated with non‐response to antidepressants and reduced amygdala reactivity among 256 patients with depression." (PMID 36168941, 2022).
depression (continued). "The expression of IL-1β in brain regions associated to pain processing, mood, and memory (such as the hippocampus and amygdala) can be associated with chronic pain perception, but also with learning deficits and depression triggered by chronic pain." (PMID 33746753, 2021). "Indeed, some genetic epidemiological studies have shown significant associations between the severity of depression and polymorphisms in inflammatory cytokine genes encoding IL-1β, IL-6, TNF and CRP." (PMID 34351967, 2021). "However, none of the previously conducted meta-analysis studies reported any association of depression or its severity with IL-6, IL-1β, and TNF-α." (PMID 34975391, 2021). "In addition, increases in the NLRP3 inflammasome and caspase-1 levels are associated with increases in serum IL-1B and IL-18 levels in patients with major depression." (PMID 34422020, 2021). "In rodents, depression-like behavior induced by the use of chronic social defeat stress, male sterility, and luteinizing hormone has been associated with higher levels of pro-inflammatory IL-1β, IL-6, and TNF-α." (PMID 34531719, 2021). "IL-1β has also been implicated in depression and could explain why fatigue and depression are so closely associated." (PMID 34249008, 2021). "Proinflammatory cytokines TNFα and IL-1β could alter the neural activity of the amygdala, which is implicated in the pathophysiology of pain, depression, and anxiety." (PMID 34025342, 2021). "Previous structural magnetic resonance imaging (MRI) studies explored the relationship between serum cytokine levels and brain morphology in healthy individuals or those with depression, and found that the hippocampal volume was inversely associated with the serum levels of IL-6, IL-1β and TNF-α." (PMID 34900691, 2021). "IL-1β is a strong modulator of corticotrophin-releasing hormone causing hypothalamic–pituitary–adrenal axis activation with increased secretion of adrenocorticotropic hormone and corticosterone, which both occur in major depression." (PMID 32495042, 2021). "This could suggest that neuronal loss and consequently cognitive deficits associated with long-term depression caused by C3 could have been counteracted by the production of Il1β, a cytokine with a neuromodulatory role on neurogenesis." (PMID 33159036, 2020). "Inflammatory cytokines, such as IL‐1β, are implicated in the pathophysiology of depression." (PMID 32125791, 2020). "Excessive IL-1β expression in the hippocampus causes psychiatric disorders such as depression." (PMID 33182607, 2020). "Previous research found that depression was associated with raised IL-1β levels; the association between PTSD and IL-1β levels found in this study could be confounded by depression." (PMID 32272662, 2020). "According to Maes and coworkers, increased interleukin production, such as Il-1β and Il-6, by monocytes in severe depression might underlie the various aspects of the immune and “acute” phase responses detectable in major depressive disorders." (PMID 32046139, 2020). "Beyond plasma cytokine levels, genetic variants of pro-inflammatory cytokines that can alter gene transcription and thereby affect inflammatory proteins, including IL-1β, have been associated with a wide range of physical and psychological disturbances, such as major depression." (PMID 30967802, 2019). "The emerging evidence indicates that P2X7R maybe plays a pivotal role in depression and mediates the IL-1β maturation, but the precise mechanisms associated with stress-induced hippocampal neuroinflammation merited further investigation." (PMID 28486969, 2017). "As a marker of inflammation measured in the periphery, high CRP may reflect activity of more upstream pro-inflammatory factors, such as IL-6 and IL-1B which may themselves induce changes in brain function predisposing to depression." (PMID 28809860, 2017).
depression (continued). "Moreover, while numerous studies have suggested a decrease in hippocampal neurogenesis associated with depression and furthermore that inflammation and specifically IL-1β has the capacity to mediate this, the mechanism(s) of action remain to be elucidated." (PMID 26775294, 2016). "The pattern of results for IL1β is consistent with previous work that identified the high expression -511C allele as a risk for poor response to pharmacotherapies for depression, and for early onset of depression and higher depressive symptom severity." (PMID 25596176, 2015). "There are some studies indicating that depression may be associated with elevated levels of IL-1β, TNF, and IL-6." (PMID 26624891, 2015). "In patients with depression and anxiety inflammatory reaction and mild chronic inflammation were observed to be caused by increased concentration of proinflammatory cytokines like TNFα, IL-1α, IL-1β, IL-4, IL-5, IL-6, IL-12, IFNγ, and C-reactive protein." (PMID 26078821, 2015). "Finally, rats exposed to systemically administered LPS and IL-1β show depressive-like behaviour and increased microglial activation in several depression associated brain regions (including hippocampus, amygdala and prefrontal cortex)." (PMID 25285951, 2014). "The results from depression-like animal model were consistent with previous reports, which indicated that life events and depressive symptoms are associated with the rise of central cytokine such as IL-1β in human MDD patents and stress-treated animals." (PMID 24444307, 2014). "Meta-analysis confirmed the association between IL-6, CRP and IL-1β levels and depression." (PMID 24244750, 2013). "Anxiety-depression status may cause changes in the IL-1β and IL-10 levels of IBS patients resulting in an imbalance of the proinflammatory and anti-inflammatory cytokines, leading to the occurrence or aggravation of IBS." (PMID 23935726, 2013). "Anxiety-depression status may cause the IL-1β and IL-10 levels in IBS patients to change and result in an imbalance of the proinflammatory and anti-inflammatory cytokines, leading to the occurrence or aggravation of IBS." (PMID 23935726, 2013). "It has been well established that IL-1β activates the hypothalamic-pituitary-adrenal axis and induces behavioral changes associated with sickness and depression, such as anhedonia, disruption of sleep, cognitive disturbances, temperature disregulation, and consumption of food." (PMID 23634700, 2013). "Furthermore, GTS-associated recovery from LPS-induced depression-like behavior was paralleled with reduced mRNA levels for IL-1β, IL-6, TNF-α, and IDO in hippocampus." (PMID 21843370, 2011). "Although no significant allelic or genotypic differences have been found between patients with depression and healthy controls, three studies have consistently shown that the G allele of rs16944 in the IL-1β gene is associated with poor response to antidepressant treatment." (PMID 21726461, 2011). "Chronic systemic inflammation in COPD may also contribute to neuroinflammatory processes that underlie depression, and elevated levels of pro-inflammatory cytokines such as IL1β, IFN-γ, IL-2, and tumor necrosis factor (TNF) have been observed in patients suffering from both COPD and depression." (PMID 41008474, 2025). "Thus, the objective of this research was to understand whether homocysteine and/or the inflammatory cytokines IFN-γ, TNF-α, IL-6, and IL-1β, may be associated with depression improvement in veterans with GWI after one month on the low-glutamate diet." (PMID 39064698, 2024). "In addition, the intake of EM reduced the abundance of Ruminococcaceae promoting the production of cytokines such as IL-1β, IL-2, and IL-6, Helicobacter inducing chronic inflammation and gastric cancer, and Alistipes causing serotonergic imbalance, anxiety and depression." (PMID 39572022, 2024).